PRL (prolactin)
Diseases named in the same sentence as PRL in open-access papers (continued):
Sharing a sentence is not in itself a finding about the gene and the disease.
Infertility (continued). "When prolactin levels rise abnormally, they cause a decrease in estrogen and progesterone production, leading to aberrant follicular development and ultimately resulting in anovulation and infertility." (PMID 40535391, 2025). "However, due to the fact that the main cause of macroprolactinemia involves anti-PRL antibodies, the diagnosis of a patient with infertility and ovulation disorders should include accompanying autoimmune diseases." (PMID 38396659, 2024). "Therefore, abnormal PRL activity, both in the blood and at the level of ovarian tissue, can cause infertility due to the mechanism of anovulation or infrequent ovulation (oligo-ovulation) secondary to hormonal imbalances." (PMID 38396659, 2024). "Sleep disturbances and stress could also be associated with higher serum prolactin levels, contributing as additional etiological factor for infertility." (PMID 39407928, 2024). "The extended use of antipsychotic drugs known to elevate prolactin levels has been associated with various health concerns, including infertility, reduced bone mineral density, and an increased risk of fragility fractures in individuals with severe mental illness." (PMID 38998877, 2024). "According to the recent research on the action of local prolactin as an inflammatory, angiogenic, and mitogenic factor, it is more probable that local, and not systemic prolactin, is involved in the pathogenesis of endometriosis and associated infertility." (PMID 39407928, 2024). "An increase in prolactin levels can inhibit the synthesis and release of gonadotropin, adversely affect the development of follicles and embryos, and cause ovulation disorders, resulting in infertility or missed abortion." (PMID 36743954, 2023). "Therefore, the problems of ovulation abnormality and infertility caused by a high concentration of PRL need to be solved." (PMID 37373417, 2023). "Most of the clinical features of prolactinoma are due to overproduction of prolactin, causing hormonal imbalance leading to menstrual abnormalities and galactorrhea in females, and in men it can cause erectile dysfunction, diminished libido, and infertility." (PMID 36337795, 2022). "In addition, while PCOS is often considered the most common cause of Hyper-PRL in infertile women, in the present study it was ranked as second." (PMID 35098010, 2021). "Thus, the currentresults in line with the previous findings, indicatedthe diminished function of orgasm to be associated withhigher prolactin levels in infertile PCOS women." (PMID 33497050, 2021). "Serum PRL isidentified as a diagnostic marker for infertility in men from ROC data analysis." (PMID 32405170, 2020). "Similarly, increased PRL levels have been implicated in the endometriosis-induced infertility, albeit a clear a causative role for PRL in the pathogenesis of endometriosis is yet to be demonstrated." (PMID 33162942, 2020). "It showed that one of the causes of infertility with unexplained etiology may be ovulation disorders caused by increased secretion of cortisol and prolactin." (PMID 33081268, 2020). "In conclusion, our study suggested that low serum PRL may be an important cause of metabolic risk in infertile PCOS patients." (PMID 32477263, 2020). "The high up-regulation of prolactin in the sera of group II-a may be one of the causes of infertility in this group." (PMID 30931169, 2019). "Overproduction of prolactin leads to cessation of menstrual periods and infertility, which may be a diagnostic clue." (PMID 23456048, 2013). "However, the deregulated PRL concentration has an inhibitory effect, which causes follicle maturation disorder, ovulation disorder and decreased endometrial receptivity, thus eventually leading to infertility." (PMID 34424219, 2021). "Thus, we speculated that the association between central adiposity and prolactin levels is influenced by the underlying causes of infertility which merits future investigations." (PMID 31455408, 2019).
Infertility (continued). "Prolactinomas hypersecrete the hormone prolactin, and the resulting elevated serum prolactin concentrations in patients may be associated in women with menstrual irregularities, infertility and galactorrhea and in men with reduced libido or erectile dysfunction." (PMID 30445560, 2019). "The Prolactin gene is an anterior pituitary hormone having close interaction with gonadotropin, i.e., the elevation in the secretion of prolactin is normally associated with the pronounced reduction in gonadotropin secretion that results in stages of infertility." (PMID 32546903, 2019). "Healthcare providers should incorporate routine hemoglobin and prolactin measurements in their evaluation of infertile women, especially in regions with high prevalence of these conditions." (PMID 40535391, 2025). "In lactating mice, suppressing endogenous prolactin secretion shortens the period of infertility, suggesting that prolactin is important for maintaining the suppression of pulsatile LH secretion during lactation." (PMID 39819370, 2025). "Taken together, our data demonstrates that long-term vortioxetine exposure induces oxidative stress, elevates catecholamine and corticosterone levels, decreases prolactin, and ultimately leads to infertility." (PMID 41304935, 2025). "Our observation that primary infertile women have a higher prevalence of elevated prolactin levels compared to women with secondary infertility corroborates findings from recent research in South Punjab, Pakistan." (PMID 40535391, 2025). "HPRL, characterized by elevated prolactin levels, disrupts the hypothalamic–pituitary–gonadal axis, leading to reproductive dysfunctions such as menstrual irregularities, anovulation and infertility." (PMID 40062901, 2025). "Elevated levels of prolactin, as predominately observed in conditions such as prolactinoma, can disrupt these processes, resulting in symptoms such as ED and infertility." (PMID 40966237, 2025). "A significant correlation was found between cortisol levels and infertility and difficulties with sexual intercourse, with elevated serum levels of cortisol and prolactin being identified in patients with endometriosis-related infertility." (PMID 40130159, 2025). "In clinical settings, these data support monitoring of menstrual function and, when necessary, evaluation of prolactin and cortisol levels during prolonged therapy, particularly in women of reproductive age or those undergoing infertility treatment." (PMID 41304935, 2025). "Combined, these data provide direct evidence that prolactin action on kisspeptin neurons is necessary for lactation-induced infertility in mice." (PMID 39819370, 2025). "Multivariable analysis identified age (OR 1.189, 95%CI 1.122–1.263, p<0.001), prolactin (OR 1.040, 95%CI 1.004–1.077, p=0.029), and triglyceride-glucose index (OR 2.473, 95%CI 1.404–4.177, p<0.001) as independent predictors of infertility." (PMID 40802395, 2025). "Studies have demonstrated higher prolactin concentrations in patients with endometriosis compared to controls, suggesting a possible role of prolactin in disease progression and infertility." (PMID 40656428, 2025). "The specific role that prolactin plays in lactational infertility, as distinct from other suckling or metabolic cues, remains unresolved." (PMID 39819370, 2025). "They highlight the importance of routine screening for both prolactin levels and anemia in women presenting with infertility, especially in resource-limited settings such as Balochistan, Pakistan." (PMID 40535391, 2025). "Our study was conducted to investigate the relationship between prolactin levels, anemia, and infertility status in women from Balochistan, Pakistan." (PMID 40535391, 2025). "Typically, the excess prolactin from macroprolactinomas results in infertility, decreased libido, and neurological and visual changes ​ ​." (PMID 41322860, 2025).
Infertility (continued). "The results of our study showed elevated levels of DHEAS, testosterone, insulin, and prolactin, highlighting the intricate hormonal imbalances that contribute to infertility in PCOS." (PMID 40802395, 2025). "The results indicate that progesterone-mediated oocyte maturation, oocyte meiosis, and the prolactin signaling pathway were significantly enriched, highlighting key metabolic distinctions between these infertility phenotypes." (PMID 40537734, 2025). "Collectively, these data show that prolactin action in the brain is absolutely required for the lactation-induced suppression of kisspeptin expression and to maintain lactational infertility in mice." (PMID 39819370, 2025). "Factors such as older age, elevated DHEAS levels, higher insulin, HOMA-IR, triglycerides, and prolactin levels were notably different between the two groups, all of which contribute to infertility in women with PCOS." (PMID 40802395, 2025). "Nevertheless, our data collectively provide strong evidence that prolactin action on arcuate kisspeptin neurons is the primary factor mediating lactation-induced infertility in mice." (PMID 39819370, 2025). "One of the first studies on this issue reported 2-fold greater baseline prolactin concentrations in the infertile patients with endometriosis compared to the normal fertile controls, but the difference was not statistically significant." (PMID 39407928, 2024). "It is well-known that infertile patients with endometriosis have an already reduced ovarian reserve, impaired follicular development, and poor oocyte and embryo quality, and these findings could be associated with ovulatory disfunction caused by the prolactin hypersecretory state." (PMID 39407928, 2024). "In another early study, the basal PRL serum levels were measured in 16 normal women and 60 women with endometriosis (37 with infertility)." (PMID 39407928, 2024). "Bromocriptine (BCR) is the most common dopamine agonist that is capable of effectively reducing the level of prolactin within the body and alleviating hypogonadism, galactorrhea, infertility, amenorrhea, and oligomenorrhea due to elevated serum PRL." (PMID 39682506, 2024). "Bromocriptine (BCR), a commonly used dopamine agonist, can reduce PRL levels in the body, thus alleviating hypogonadism, infertility, galactorrhea, oligomenorrhea, and amenorrhea due to serum PRL elevation." (PMID 38997985, 2024). "Significant differences in the prolactin serum levels were only registered between the group of infertile patients with endometriosis stages III/IV compared to infertile patients without endometriosis." (PMID 39407928, 2024). "In infertile patients, we observed via a correlation analysis, an inverse correlation between PRL and sperm motility, and a direct correlation of TAC with PRL and fT4, but not with gonadotropins or gonadal steroids." (PMID 39199179, 2024). "Taken together, these data are highly suggestive of the possible connection between local prolactin action and the development of endometriosis-induced infertility." (PMID 39407928, 2024). "Increased serum prolactin levels are a common finding in the work-up of patients with complaints of menstrual irregularity and infertility." (PMID 38578472, 2024). "Serum PRL levels should only be measured in symptomatic patients, with symptoms such as galactorrhea, menstrual irregularity, infertility and decreased libido." (PMID 38765533, 2024). "No statistical significance was observed in weight, BMI, infertility type, infertility duration, basal level of LH, estrogen (E2), progesterone (P), prolactin (PRL) progesterone (P), AFC, fasting blood glucose, HOMA-IR, and total Gn usage (P > 0.05)." (PMID 38807145, 2024). "The following twelve factors were subjected to univariate analysis: patient age, duration of infertility, cause of infertility, type of protocol used, induction length in days, type of medication, AFC, FSH, TSH, level of estradiol, level of prolactin, and AMH." (PMID 38714986, 2024).
Infertility (continued). "In a study performed in a group of infertile patients we found an inverse correlation between prolactin (PRL) and sperm motility, and a direct correlation of TAC with PRL and free thyroxine (fT4), but not with gonadotropins or gonadal steroids." (PMID 36902424, 2023). "Their results showed a significantly lower PRL in women with PCOS than infertile controls in each age group, even after adjusting for BMI." (PMID 38004264, 2023). "Meanwhile, most infertile sheep are accompanied by significantly elevated levels of PRL in the blood." (PMID 37833858, 2023). "Several habits and lifestyle factors influenced prolactin as its serum concentration was significantly modified by marijuana use, tobacco smoking, and sedentary in infertile men." (PMID 36303626, 2022). "We report a particular case of a spontaneously occurring pregnancy in a long-term amenorrheic patient due to a prolactinoma with high serum prolactin (PRL) following the failure of dopamine agonist therapy (DA) for infertility." (PMID 36556282, 2022). "Another proposed hormone linking OSA and infertility is the abnormal secretion of prolactin (PRL) after sleep fragmentation and hypoxia." (PMID 35743718, 2022). "In our healthcare system, serum assays for prolactin are readily accessible for all those receiving health care for AUB or infertility." (PMID 35983674, 2022). "Serum PRL should be measured in suspected cases of prolactinoma: women with irregular menstruation, amenorrhea, infertility, or galactorrhea, and men with decreased libido." (PMID 35892862, 2022). "The groups were matched for age, duration of infertility, prolactin, follicle stimulating hormone (FSH), thydroid stimulating hormone (TSH), luteinizing hormone (LH), and estradiol levels." (PMID 34872141, 2021). "One study examining prolactin levels in infertile men observed increased prolactin levels in men with asthenozoospermia, oligozoospermia, and azoospermia." (PMID 33807489, 2021). "A study on 87 infertile women aged 31-40 yr with Hyper-PRL showed that 75.8% of participants suffered from microadenoma." (PMID 35098010, 2021). "In the present study, idiopathic Hyper-PRL was the most common reason for Hyper-PRL with a frequency of 47.3% in infertile participants." (PMID 35098010, 2021). "One study of infertile women with Hyper-PRL reported that the mean duration of infertility was 9.1 yr." (PMID 35098010, 2021). "This evidence provides the rationale for further investigation on the role of PRL in the pathogenesis of endometriosis, as well as on the potential beneficial effects of dopamine agonists for the treatment of endometriosis-related infertility." (PMID 33162942, 2020). "In the infertile group, higher levels of PRL and COR were observed than that of in the control group." (PMID 33081268, 2020). "In conclusion, elevated secretion of COR and PRL in infertile women impairs the menstrual cycle by decreasing the pre-ovulatory LH peak and E2 and postovulatory E2 levels that affect the endometrial growth, and consequently reduce the chances to conceive." (PMID 33081268, 2020). "Despite of numerous studies, little is known about the correlation between serum PRL and metabolism in infertile females." (PMID 32477263, 2020). "LH, FSH and PRL levels were significantly increased in azoospermic, oligozoospermic and asthenozoospermic infertile maleswhile FSH and PRL were significantly elevated in normozoospermic infertile group." (PMID 32405170, 2020). "Two groups were comparable in terms of age, BMI, basal FSH, E2, LH, TSH, and PRL levels, duration of infertility, and percentage of patients with unexplained infertility and male subfertility." (PMID 32831851, 2020). "Age (woman and man), infertility years, basic PRL, and AMH showed significant differences in different age groups." (PMID 33343511, 2020).
Infertility (continued). "Such a discrepancy has been reported also in studies evaluating PRL levels in the peritoneal fluid of infertile women with endometriosis, where PRL levels have been found similar or increased." (PMID 33162942, 2020). "Among patients with unexplained causes of infertility, WC, WHtR and WHR showed a significant partial correlation to prolactin." (PMID 31455408, 2019). "Other researchers also showed a positive correlation between FRAP and PRL in unexplained infertility, suggesting that increased levels of antioxidants prevent ROS-induced oxidative damage." (PMID 30999628, 2019). "According to our results, longer duration of infertility and galactorrhea wereassociated with increased miscarriage rates, although miscarriage patients did nothave higher serum prolactin levels." (PMID 31056891, 2019). "Serum prolactin levels were significantlyhigher among infertile women with endometriosis than in infertile women withoutendometriosis (p=0.003)." (PMID 30969738, 2019). "This study also observed a negative association between central adiposity indices (WC and WHtR) and prolactin levels in both primary and secondary infertile women." (PMID 31455408, 2019). "Mean prolactin levels of the fertile group(14.4 ± 5.4 ng/mL) were higher than the infertile group’s(12.2 ± 4.6 ng/mL)." (PMID 29707935, 2018). "LH, FSH and prolactin: Following their detection in seminal plasma, the levels of gonadotropins and prolactin have been compared in fertile and infertile men." (PMID 29046808, 2017). "Kisspeptin administration can also restore gonadotropin secretion and ovarian cyclicity in a prolactin-induced infertility model in mice." (PMID 27901187, 2016). "The ATD-positive and -negative groups were similar for age, body mass index (BMI), cause of infertility, serum TSH levels and serum concentrations of E2, PRL and LH in the early follicular phase." (PMID 26391773, 2015). "Linear regression analysis showed that amongst the variables age, duration of infertility and endometriosis, only age (p=0.03, β=0.38) and endometriosis (p=0.01, β=5.65) had a significant difference with prolactin level." (PMID 26000006, 2015). "Pre-clinical and clinical evidence was found for Vitex agnus-castus for lowered prolactin, improved menstrual regularity and treatment of infertility." (PMID 25524718, 2014). "Significantly increased serum T and LH and reduced levels of FSH and PRL in infertile men were observed." (PMID 25215296, 2014). "Indications for testing serum PRL levels include the following: menstrual irregularities, galactorrhea, infertility, and/or alterations in libido." (PMID 24194758, 2013). "The infertility of these mice appears to be due to the very high prolactin levels in young adults, because it can be reversed by temporary inhibition of prolactin secretion by cabergoline." (PMID 23226476, 2012). "We collected descriptive, quality and outcome data (tumor growth, visual field defects, infertility, sexual dysfunction, amenorrhea/oligomenorrhea and prolactin levels)." (PMID 22828169, 2012). "Additionally, elevated levels of DHEAS, testosterone, insulin, and prolactin highlight the intricate hormonal imbalances that contribute to infertility in this population." (PMID 40802395, 2025). "Several studies show high prolactin levels in infertile women." (PMID 40535391, 2025). "Increased levels of prolactin can be the reason for infertility by elevating hypothalamic dopamine release, which in turn inhibits gonadotropin-releasing hormone (GnRH) and prevents gonadal steroidogenesis and ultimately infertility." (PMID 40535391, 2025). "Additionally, they found associations with increased levels of reactive oxygen species (ROS), decreased testosterone and luteinizing hormone, and increased prolactin and follicle-stimulating hormone in the infertile group." (PMID 39968364, 2024).